IDH1 (isocitrate dehydrogenase (NADP(+)) 1)
Diseases named in the same sentence as IDH1 in open-access papers (continued):
Sharing a sentence is not in itself a finding about the gene and the disease.
cholangiocarcinoma (continued). "Another study showed that ivosidenib (AG-120) targeted IDH1 mutations could improve survival outcomes in participants with histologically confirmed IDH1-positive chemotherapy-refractory cholangiocarcinoma, with a PFS of 2.7 months (IQR 1.6-4.2)." (PMID 35311147, 2022). "Therefore, identifying effective leading compounds which are capable of inhibiting IDH1-R132H mutations is promising in drug improvement and cholangiocarcinoma treatment." (PMID 35802554, 2022). "The present study intends to clarify the hypothesis that isocitrate dehydrogenase 1 (IDH1) mutation in cholangiocarcinoma impairs tumor progression by sensitizing cells to ferroptosis through the in vitro and in vivo experiments." (PMID 35600114, 2022). "Taken together, AG120 and IDH305 could reverse IDH1 mutation effects on erastin-induced ferroptosis in cholangiocarcinoma." (PMID 35600114, 2022). "Therefore, gain-of-function mutations in IDH1 or IDH2 are important triggering events in the development of cholangiocarcinoma." (PMID 35154988, 2022). "This study may provide a potential mechanism for better understanding the role of IDH1 mutation in cholangiocarcinoma." (PMID 35600114, 2022). "Taken together, IDH1 mutation could aggravate erastin-induced ferroptosis in cholangiocarcinoma by increasing lipid ROS." (PMID 35600114, 2022). "A phase III study including 185 patients with advanced IDH1-mutant cholangiocarcinoma caused significant improvement in progression-free survival (median 2.7 months vs. 1.4 months; HR: 0.37, P < 0.001) when treated with an IDH1 inhibitor named ivosidenib compared to placebo." (PMID 35530316, 2022). "Combined with the findings from previous studies, this study aimed to explore whether IDH1 mutation in cholangiocarcinoma impairs tumor progression by sensitizing cells to erastin-induced ferroptosis." (PMID 35600114, 2022). "The inhibition of the IDH1 mutation through its inhibitor ivosidenib represents a recent breakthrough in second-line therapy for cholangiocarcinoma, dramatically improved median PFS (2.7 months vs 1.4 months, HR = 0.37, one-sided p < 0.0001) compared with placebo." (PMID 34012920, 2021). "Ivosidenib showed improved PFS in patients with cholangiocarcinoma harboring IDH1 mutation." (PMID 33879235, 2021). "The safety and efficacy of Ivosidenib, an inhibitor of mutated IDH1, have been investigated in a multicenter randomized double-blinded placebo-controlled phase 3 trial among patients with advanced cholangiocarcinoma who had progressed on either fluorouracil or gemcitabine-based chemotherapy." (PMID 34680318, 2021). "However, IDH1-mutations are detected in only 13-15% of patients with cholangiocarcinoma and FGFR-2 fusion in only about 13-15% of patients with iCCA." (PMID 34858809, 2021). "In the present study, we identified a high frequency of mutated IDH1 in cholangiocarcinoma." (PMID 32373065, 2020). "In the present study, we aimed to explore the effects of IDH1 mutation on cholangiocarcinoma." (PMID 32373065, 2020). "Furthermore, we revealed the mechanisms of IDH1 mutation underlying the tumor progression of cholangiocarcinoma." (PMID 32373065, 2020). "In 2012, Borger and colleagues have revealed IDH1 mutations in cholangiocarcinoma." (PMID 32373065, 2020). "Mutations in IDH1 occur in up to 25% of cholangiocarcinomas." (PMID 32373065, 2020). "Recently, CA9 and IDH1 were reported to be diagnostic factors for cholangiocarcinoma." (PMID 30849962, 2019). "Mutations in Isocitrate Dehydrogenase 1/2 (IDH1/2) are frequently observed in cholangiocarcinoma (CCA)." (PMID 39156971, 2024).
cholangiocarcinoma (continued). "FDA has approved several targeted therapies for cholangiocarcinoma (CCA), including drugs that target IDH1 mutation and fibroblast growth factor receptor 2 (FGFR2) fusions in genetically selected populations." (PMID 37814942, 2023). "As a frequently occurring molecular event in leukemia, brain cancer and cholangiocarcinoma (CCA), the clinical impact of IDH1 R132 – mutation direct diagnostics or therapeutics varies largely between different tissues." (PMID 38086797, 2023). "Notably, both FGFR2 fusions and IDH1 mutations are rare in fluke-associated cholangiocarcinomas." (PMID 37891989, 2023). "In CCA, the most common mutations of IDH1 are R132C (more frequent), R132G and R132L, which are distinct from the R132H mutation found in gliomas; nevertheless, these activating alterations have been shown to increase the serum level of 2-HG in cholangiocarcinoma." (PMID 32138158, 2020). "Ivosidenib, an inhibitor targeting mutant IDH1, is approved for treating IDH1-mutated malignancies, including AML and cholangiocarcinoma." (PMID 40342735, 2025). "Tibsovo (Ivosidenib) is an FDA-approved therapy for the treatment of cholangiocarcinoma and R/R AML patients with IDH1 mutation." (PMID 40863132, 2025). "In this article, we briefly review the FastTrack identification of IDH1/2 alteration of cholangiocarcinoma." (PMID 40075667, 2025). "The successful clinical implementation of FGFR2 and IDH1 inhibitors underscores the feasibility and therapeutic value of molecularly tailored interventions in the management of cholangiocarcinoma." (PMID 41008657, 2025). "Given that ivosidenib has already received regulatory approval for IDH1-mutant cholangiocarcinoma, the evaluation of this agent in IDH1-mutant CS models would be of particular translational relevance once such models are established." (PMID 41419593, 2025). "A notable breakthrough in this context is the identification of isocitrate dehydrogenase (IDH) mutations, particularly IDH1 and IDH2, which occur in a subset of cholangiocarcinoma patients." (PMID 40075667, 2025). "Both the IdyllaTM IDH1-2 Mutation Assay Kit as a FastTrack method and Next-Generation Sequencing (NGS) panels play critical roles in molecular characterization of cholangiocarcinoma." (PMID 40075667, 2025). "IDH1 inhibitor Ivosidenib has shown efficacy in clinical trials, offering new hope for patients with IDH1-mutant cholangiocarcinoma." (PMID 40075667, 2025). "For instance, Ivosidenib, an IDH1 inhibitor, has shown efficacy in clinical trials, offering a new therapeutic option for patients with IDH1-mutant cholangiocarcinoma." (PMID 40075667, 2025). "In conjunction with FGFR2 fusions, Isocitrate dehydrogenase 1 (IDH1) mutations, the BRAF p.V600E hotspot, and others are found in approximately 30–40% of patients with cholangiocarcinoma, particularly intrahepatic subtypes." (PMID 41153346, 2025). "Meanwhile, ivosidenib can be used to treat IDH1 mutant cholangiocarcinoma with significant survival benefits." (PMID 39575391, 2024). "The conversion of IDH1 R132C to IDH1 R132F and the acquired isoform mutation of IDH2 R172V have been reported in patients with IDH1-mutated cholangiocarcinoma who develop resistance to ivosidenib as a result." (PMID 39273177, 2024). "The median survival rate for chemotherapy-refractory IDH1-mutant cholangiocarcinoma patients receiving ivosidenib therapy is 2.7 months, while that of patients treated with a placebo is 1.4 months." (PMID 39273177, 2024). "In the ClarIDHy study, the IDH1 inhibitor ivosidenib demonstrated a clinical benefit in previously treated, advanced IDH1-mutant cholangiocarcinoma and has gained approval for second-line treatment." (PMID 38429607, 2024). "Targeting the mutant IDH1/2 has opened a novel therapeutic avenue for ICC patients with IDH1 mutations, and the FDA have approved the mutant IDH1 inhibitor ivosidenib for treating IDH1-mutated advanced cholangiocarcinoma." (PMID 39273177, 2024).
cholangiocarcinoma (continued). "Approximately 20% of cholangiocarcinomas harbor IDH1 and IDH2 mutations; ivosidenib has been approved for treating IDH1-mutant CCA." (PMID 39610917, 2024). "Molecular targets such as FGFR2 fusion, IDH1/2 mutation, and HER2 amplification are currently being evaluated for targeted treatment approaches in cholangiocarcinoma (CCA), with most of these strategies still in the clinical investigation phase." (PMID 39199633, 2024). "Genetic alterations detected in cholangiocarcinomas include fusions and mutations in FGFR2, mutations in IDH1 and KRAS, the BRAF V600E mutation, and ERBB2 amplification." (PMID 37108676, 2023). "The IDH-1 inhibitor ivosidenib was shown to improve PFS versus placebo (2.7 vs. 1.4 months, p < 0.0001) among 124 patients with metastatic IDH1-mutated cholangiocarcinoma in a phase III trial." (PMID 38203714, 2023). "Therapies targeting FGFR and IDH-1 have gained FDA approval after progression on front-line therapies for patients with cholangiocarcinoma." (PMID 38203714, 2023). "For patients who harbor IDH1-mutant cholangiocarcinoma and who had progressed on previous therapy, the Phase III ClarIDHy trial showed a meaningful clinical benefit for the IDH1-Inhibitor ivosidenib compared with placebo." (PMID 36765942, 2023). "BRAF, erb-b2 receptor tyrosine kinase 2 (ERBB2), fibroblast growth factor receptor 2 (FGFR2), and isocitrate dehydrogenase 1 (IDH1) genes have been reported as therapeutically relevant genomic alterations in cholangiocarcinoma patients." (PMID 37108676, 2023). "Ivosidenib for IDH1 p.Arg132Leu aberration (case 2) was the FDA’s approved therapeutic drug for the management of advanced cholangiocarcinoma patients." (PMID 35008396, 2022). "Ivosidenib (AG-120) is the first oral targeted inhibitor of IDH1 that has demonstrated benefit in pretreated IDH1-mutant advanced cholangiocarcinoma patients." (PMID 35406572, 2022). "A better understanding of the mechanisms of ivosidenib resistance in IDH1-mutated IHCC will help inform the next generation of therapeutic strategies to target mutant IDH1 in cholangiocarcinoma." (PMID 36056177, 2022). "The following keywords and Boolean operators (“AND”, “OR”) were used for the narrative review: “IDH1 mutant cholangiocarcinoma,” “Cholangiocarcinoma,” “Ivosidenib OR Tibsovo,” and “Ivosidenib OR Tibsovo AND Cholangiocarcinoma”." (PMID 35154988, 2022). "Consistently, the lipid ROS levels in erastin-treated IDH1 mutation cell line was increased compared to that in erastin-treated IDH1 knockout or WT cell line, indicating that IDH1 mutation could aggravate erastin-induced ferroptosis in cholangiocarcinoma by increasing lipid ROS." (PMID 35600114, 2022). "Ivosidenib shows efficacity in IDH1 mutant cholangiocarcinoma and BRAF inhibitors dabrafenib and trametinib in patients with BRAF V600E mutations." (PMID 35484217, 2022). "A relevant study shows that IDH1 and IDH2 mutations predominate in cholangiocarcinoma, while IDH2 contributes only partially (2–6%)." (PMID 35802554, 2022). "In conclusion, targeted therapies directed against mutant IDH1 have opened a new therapeutic avenue for patients with IHCC with IDH1 mutations, and the FDA recently approved ivosidenib for previously-treated IDH1-mutated advanced cholangiocarcinoma." (PMID 36056177, 2022). "Based on results of large clinical trials, targeted therapy drugs pemigatinib and ivosidenib have been approved by FDA to treat cholangiocarcinoma patients with FGFR2 fusions and IDH1 mutations, respectively." (PMID 34720757, 2021). "In our cohort, the frequencies of IDH1 mutations and FGFR2 fusions detected by ctDNA profiling in cholangiocarcinoma were 7.4 and 4.8%, respectively." (PMID 34720757, 2021). "An IDH1/2-targeted drug, ivosidenib, was evaluated in a randomized phase III study involving 185 patients with pretreated IDH1/2-mutated cholangiocarcinoma." (PMID 34681592, 2021).
cholangiocarcinoma (continued). "In this context, a phase 3, randomized, double-blind study (ClarIDHy) randomized (2:1) 185 patients with IDH1-mutant cholangiocarcinoma, previously treated with up to 2 treatment regimens, to receive a mutated IDH1 inhibitor, ivosidenib (AG-120), or placebo." (PMID 33660222, 2021). "IDH1 inhibitors, most notably ivodesinib, as shown in the ClarIDHy trial, have shown promise in improving survival in patients with cholangiocarcinoma." (PMID 34945742, 2021). "In the ClarIDHy trial, the small molecule inhibitor Ivosidenib provided a survival advantage in pretreated patients with IDH1-mutant cholangiocarcinoma, thus expanded the armamentarium against this molecular subtype of disease." (PMID 33182517, 2020). "The mutations in IDH1 affected the expression of α-KG and NADPH, thereby impacting mitochondrial functions in cholangiocarcinoma." (PMID 32373065, 2020). "We further revealed that IDH1 mutation reduced the levels of α-KG and NADPH, and IDH1 regulated the expressions of ALDH1 in cholangiocarcinoma." (PMID 32373065, 2020). "This review examines the molecular rationale and the results of preclinical and early-phase studies on novel pharmacological agents targeting mutant IDH1 in cholangiocarcinoma patients." (PMID 32824685, 2020). "Mutations in isocitrate dehydrogenase (IDH)-1 or -2 (which we commonly refer to as IDH) are found in gliomas (60–80%, acute myeloid leukemia (~20%), cholangiocarcinomas (7–28%) and in benign and malignant central cartilaginous tumours." (PMID 28484589, 2017). "In an evaluation of 45 clinical tumor RNA specimens spanning pancreatic, cholangiocarcinoma, and colorectal cancers, the assay correctly classified mutation status with full concordance for KRAS G12D, IDH1 R132C and BRAF V600E, with a subset of positive cases corroborated by orthogonal RT-ddPCR." (PMID 42080370, 2026). "Notably, ivosidenib has already received FDA approval for previously treated IDH1-mutant cholangiocarcinoma, demonstrating clinically meaningful improvements in both progression-free and overall survival." (PMID 41487574, 2025). "Thus Ivosidenib, an IDH1 inhibitor, provides a new therapeutic option for patients with IDH1-mutant cholangiocarcinoma." (PMID 40075667, 2025). "In addition, a Phase 3 clinical trial showed improved progression-free survival in patients with advanced, IDH1-mutant cholangiocarcinoma treated with ivosidenib compared with placebo (median 2.7 months [95% CI 1.6–4.2] vs. 1.4 months [1.4–1.6])." (PMID 41551874, 2025). "In cholangiocarcinoma, NTRK1-3 fusions are estimated to occur in about 3.6% of cases, particularly intrahepatic subtypes, and represent one of the few actionable alterations beyond FGFR2 fusions and IDH1 mutations." (PMID 41153346, 2025). "ERBB2 amplification was the most common predictive marker in gastroesophageal adenocarcinoma, and recent targeted therapy approvals and guideline updates had a significant impact for patients with cholangiocarcinoma and actionable findings in IDH1 (11.2%), FGFR2 (8.1%), or BRAF (1.8%)." (PMID 37682776, 2024). "Additionally, IDH1 is involved in cholangiocarcinoma by inducing the GPX4-regulated ferroptosis pathway." (PMID 38536014, 2024). "Twelve (17.9%) clinical trials dealt with isocitrate dehydrogenase (IDH) 1/2 targeting therapy either in combination with cisplatin (Cis) and gemcitabine (Gem) as first-line treatment for BTCs or in monotherapy in patients with IDH1 mutant advanced malignancies, including cholangiocarcinoma (CCA)." (PMID 36045702, 2021). "In addition, these studies have also identified new, recurrent driver genetic alternations in cholangiocarcinoma, such as FGFR2 fusion and IDH1 mutations that are potentially actionable with available pan-FGFR inhibitors and IDH1 inhibitors." (PMID 33451059, 2021). "This study shows the clinical benefit of ivosidenib in advanced, IDH1-mutant cholangiocarcinoma." (PMID 33451059, 2021).
cholangiocarcinoma (continued). "Results of a phase 1 study suggest that ivosidenib is a well-tolerated option in patients with IDH1-variant cholangiocarcinoma, and phase 3 study shows progression-free survival was significantly improved with ivosidenib compared with placebo in advanced, IDH1-mutant cholangiocarcinoma." (PMID 33803322, 2021). "In the present study, we further verified the effects of IDH1 on cholangiocarcinoma." (PMID 32373065, 2020). "Therefore, we verified that IDH1 was associated with the levels of α-KG and NADPH in cholangiocarcinoma." (PMID 32373065, 2020). "In contrast, non-liver fluke-associated cholangiocarcinoma has been shown to harbor high copy-number aberrations, PD-1/PD-L1 expression, epigenetic mutations involving IDH1/2 and BAP-1, and FGFR/PRKA-related gene rearrangement." (PMID 33182517, 2020). "Moreover, Ivosidenib, an inhibitor of mutated IDH1 has shown encouraging results in a phase I trial including patients with CCA33 and is evaluated in a phase III trial in advanced cholangiocarcinoma (ClinicalTrials.gov identifier: NCT02989857)." (PMID 31519967, 2019). "A recent study found that neutralization of CC2 can improve survival and remodel the tumor microenvironment in isocitrate dehydrogenase 1 (IDH1)-mutant cholangiocarcinoma (CCA), a highly aggressive sub-type of CCA." (PMID 40426911, 2025). "As previously discussed, IDH1 and IDH2 mutations establish an immunologically cold background with low lymphocyte infiltrates at the tumor site; the treatment with Ivosidenib has been proved to be able to recruit CD8+ T cells and restore immune system tumor vulnerability in cholangiocarcinoma." (PMID 39123479, 2024). "Besides, since excessive accumulation of lipid ROS is a critical cause of ferroptosis, the subsequent assay was performed to determine whether mutant IDH1 could promote the sensitivity of cholangiocarcinoma to erastin by increasing lipid ROS." (PMID 35600114, 2022). "Studies have shown that upwards of 60% of cholangiocarcinoma (CCA) contain such aberrations, including those in isocitrate dehydrogenase-1 (IDH1), fibroblast growth factor receptor-2 (FGFR2), and neurotrophic tyrosine receptor kinase (NTRK)." (PMID 35626165, 2022). "Several targeted therapies have received approval for cholangiocarcinoma treatment, including inhibitors of FGFR (futibatinib, pemigatinib, and infigratinib), IDH1 (ivosidenib), and MSI-high/TMB-high (pembrolizumab), and NTRK (larotrectinib, entrectinib)." (PMID 38730642, 2024). "Ivosidenib, an oral IDH1 inhibitor, has been studied in a phase III clinical trial (ClarIDHy) for patients with pretreated IDH1 mutant cholangiocarcinoma." (PMID 38559612, 2024). "The relationship between IDH1 mutation isotype and 2-HG inhibition was not investigated in this study, as a previous phase 1 study showed the median values of 2-HG inhibition based on AUC were comparable between the different isotypes in subjects with cholangiocarcinoma." (PMID 38278871, 2024). "The indications for the IDH1 inhibitor, ivosidenib, extend to IDH1 mutant AML and IDH1 mutant cholangiocarcinoma." (PMID 36254250, 2022). "Finally, the abundance of IDH1/2 mutations in gliomas and cholangiocarcinomas, but lack of TET2 mutations, are likely a reflection of TET enzymes functioning in tissue specific patterns—TET1, for example, has very recently been shown to be an oncogenic driver in IDH‐wt cholangiocarcinoma." (PMID 36618446, 2021). "Additional efforts to test the combination of olaparib and AZD6738 is underway in phase II trial in IDH1- and IDH2-mutant cholangiocarcinoma and solid tumors, led by LoRusso and colleagues at our institution (NCT03878095)." (PMID 34027408, 2021). "Notably, IDH1 and IDH2 mutations, which are common (approximately 25%) in cholangiocarcinoma (CCA) patients of Western populations 21, were observed in only 7% and 2% of Chinese BTC patients, respectively." (PMID 33754015, 2021).